INS (insulin)
Diseases named in the same sentence as INS in open-access papers (continued):
Sharing a sentence is not in itself a finding about the gene and the disease.
Insulin resistance (continued). "The homeostasis model assessment insulin resistance (HOMA‐IR) index, quantitative insulin sensitivity check index (QUICKI), triglyceride‐to‐HDL‐C ratio (TG/HDL‐C) and Pediatric Score Index for Metabolic Syndrome (PsiMS) were calculated." (PMID 35194980, 2022). "All three studies evaluating the impact of vitamin E supplementation on insulin resistance showed decreased HOMA score and insulin levels." (PMID 35388031, 2022). "Supplementation with probiotics ↓FBG, serum insulin, TG, and VLDL-c, and improved insulin resistance indexes." (PMID 35052633, 2022). "Alterations in some insulin signaling pathways such as PI3K/Akt and GSK-3 are present in central inflammation and insulin resistance." (PMID 35615716, 2022). "The present results showing the HFD increased the levels of glycated hemoglobin, glucose, and insulin in the blood and the abnormal expansion of pancreatic α/β cells consolidate the concept that the HFD induces hyperglycemia with insulin resistance." (PMID 35453415, 2022). "Insulin levels during the OGTT were significantly increased at fasting and at the 30 minutes time point in the r-Severe group, suggesting increased insulin resistance, in agreement with higher HOMA-IR and decreased QUICKI index values." (PMID 35435140, 2022). "This situation was mimicked in our patients with solid correlations with glucose homeostasis parameters, especially FGF21, fasting insulin, and HOMA1-IR, the latter two reflecting whole-body insulin resistance." (PMID 35160008, 2022). "Through the ITT test, we calculated the relative value of blood glucose decline, insulin resistance index (HOMA-IR) and Quantitative insulin sensitivity check index (QUICKI)." (PMID 35907871, 2022). "A significant decrease was observed in blood glucose and insulin levels, together with a significant improvement in HOMA-IR, insulin resistance was significantly decreased, falling below the HOMA-IR threshold of 2.5." (PMID 34532829, 2022). "Post-mortem examination of insulin signaling in the hippocampi of AD patients revealed markedly attenuated activation of IRS-1 phosphorylation on Ser 616, a biomarker of insulin resistance, and correlated with Aβ plaque burden in these brains." (PMID 35798912, 2022). "While insulin resistance may be a useful predictor of subsequent hypertension, we are not aware of studies which have detailed metabolic data in pregnancy enabling study of the relevance of insulin sensitivity to the development of hypertension in the long term." (PMID 33536549, 2022). "In mice with insulin resistance induced by a HFD, metformin enhances insulin action by reversing the reduced ATP production and oxidative stress in an AMPK-independent way." (PMID 35955427, 2022). "Individuals in the SIRD subgroup were the most insulin resistant, whereas those in the MARD subgroup were the oldest at diagnosis, with the lowest blood glucose levels and lowest degree of insulin resistance." (PMID 34689214, 2022). "As inflammation is a key mechanistic link between obesity and insulin resistance, these findings strongly suggest LRG1 promotes insulin sensitization via modulation of inflammation and cell death during adipose tissue remodeling." (PMID 36346018, 2022). "The homeostatic model assessment of insulin resistance (HOMA-IR) was calculated from fasting glucose and insulin levels." (PMID 35597962, 2022). "Treatment of adipocytes and hepatocytes with LTB4 in vitro induces insulin resistance, and knockout of BLT-1 can improve adipose tissue inflammation and insulin sensitivity in obese mice." (PMID 36230963, 2022). "FABP4 plays a crucial role in the regulation of glucose/lipid metabolism and insulin sensitivity: FABP4-null mice are protected from HFD-induced hyperglycaemia, hyperinsulinaemia, and insulin resistance." (PMID 35628332, 2022).
Insulin resistance (continued). "Following the decrease in glycemia, blood concentrations of insulin also reduced in the diabetic NHPs treated with FTY720, in parallel, the calculated insulin resistance indices (HOMA‐IR) decreased, indicating improvement of tissue insulin sensitivity." (PMID 35064580, 2022). "TSH, thyroid-stimulating hormone; HOMA-IR, homeostatic model assessment of insulin resistance; QUICKI, quantitative insulin sensitivity check index." (PMID 36465194, 2022). "Glucose, insulin, and HOMA-IR were assessed at the end of the 8-week intervention as markers of whole-body insulin resistance." (PMID 35725493, 2022). "This increase in insulin and HOMA-IR was decreased by both formulations A and B significantly, indicating a possible preventive effect of the formulations on insulin resistance of treated mice." (PMID 35707380, 2022). "Compensatory hyperinsulinemia that ensues excessive dietary carbohydrate intake or early-stage insulin resistance in overweight or obese patients may provoke macrophages to release proinflammatory cytokines like IL-1β, which in turn may render insulin target cells insulin-resistant." (PMID 36177037, 2022). "Central estrogen signaling is suggested to be involved in insulin sensitivity, as intact obese female mice are protected from DIO-induced insulin resistance in NPY/AgRP neurons." (PMID 35757435, 2022). "Age-related defects in the insulin signaling cascade, such as a reduction in insulin-stimulated tyrosine phosphorylation, are more severe in adipose tissue than in either the liver or muscle, which suggests that adipose tissue may be an origin of insulin resistance during the aging process." (PMID 35379822, 2022). "The NLR significantly positive correlated to the insulin level at T0 and POM3, as well as insulin resistance at POM3." (PMID 36147694, 2022). "To investigate changes in insulin resistance, we used the homeostasis model assessment of insulin resistance (HOMA-IR) and insulin sensitivity index (ISI) to evaluate the effect of RB on insulin resistance in KKAy mice." (PMID 35571083, 2022). "High‐fat diet feeding lead to an increase in fasting serum glucose level, insulin level, and HOMA‐IR index, which suggested insulin resistance in HFD‐fed rats." (PMID 36348812, 2022). "C carriers in NAFLD patients had higher homeostatic model assessment for insulin resistance (HOMA-IR) and fasting insulin compared to G carriers." (PMID 36035124, 2022). "This reveals crosstalk at the hypothalamic level involving resistin, insulin, adiponectin, and FGF21 signaling pathways, which would be involved in HFD-induced neuroinflammation and insulin resistance." (PMID 36078135, 2022). "Insulin resistance was determined by HOMA-IR as calculated using fasting glucose and fasting insulin levels." (PMID 35370955, 2022). "Primary outcomes included fasting blood glucose (FBG), 2-h postprandial blood glucose (2hPG), glycosylated hemoglobin, type A1c (HbA1c), fasting serum insulin (FINS), and homeostasis model assessment of insulin resistance (HOMA-IR)." (PMID 36160405, 2022). "The insulin levels or HOMA-IR increased significantly in the db/db and db/db+HFD groups, indicating a potential insulin resistance, and the insulin levels or HOMA-IR decreased after the Ab treatment." (PMID 36499639, 2022). "Clusterin in HDL is related to insulin sensitivity, whereas clusterin in LDL is closely correlated with insulin resistance." (PMID 36553017, 2022). "IGF-1 is essential for normal insulin sensitivity, and dysregulation of IGF-1 synthesis results in the development of insulin resistance." (PMID 35745205, 2022). "Significant reductions in glycated haemoglobin(HbA1c), fasting plasma glucose(FPG), 2-hour postprandial blood glucose(2hPG), fasting insulin(FINS) and homeostasis model assessment of insulin resistance(HOMA-IR) have been found after treatment with CHFs." (PMID 36187136, 2022).
Insulin resistance (continued). "In this experiment, compared with the control group, rats in the model group had obvious symptoms of early insulin resistance in T2DM, such as abnormally elevated serum insulin levels and decreased insulin sensitivity." (PMID 36353458, 2022). "Insulin resistance increases during puberty, potentially altering CFRD status, although the decline in sensitivity is accompanied by compensatory insulin secretion and recovery after completion of puberty." (PMID 35431976, 2022). "ERK inhibition can result in insulin resistance by down‐regulating insulin‐like receptor gene expression and ERK‐mediated physiological adjustment of insulin sensitivity allows maintenance of glucose homeostasis." (PMID 34053181, 2021). "IGF1 bears 50% homology to insulin and have the same hypoglycaemic effect, with many studies linking fluctuation in IGF1 levels with metabolic disorder and insulin resistance." (PMID 34940355, 2021). "Indeed, pathological conditions related with insulin resistance, such as obesity and type 2 diabetes, are frequently associated with lower hepatic IDE expression and activity, while physical exercise, which improves insulin sensitivity, is associated with higher hepatic IDE expression and activity." (PMID 34054736, 2021). "Regarding hematological and biochemical parameters related to inflammation in OW/OB schoolchildren, leukocytes, platelets and NLR were higher in boys with insulin resistance, as measured by the HOMA-IR index, than in those with insulin sensitivity." (PMID 35601749, 2021). "All participants were assessed for whole blood selenium concentration, fasting plasma insulin and glucose, HbA1c, and HOMA-IR (Homeostatic Model Assessment for Insulin Resistance)." (PMID 34262926, 2021). "Inhibition of the NFκB pathway with PS1145 in turn reduced food intake and diminished hypothalamic insulin resistance in mice fed a HFD, identifying a targetable pathway to restore hypothalamic insulin signaling." (PMID 34831343, 2021). "In both control and insulin-resistant differentiated mouse 3T3-L1 adipocytes, FXR knockdown enhanced the insulin resistance and attenuated the effects of DMRT2 overexpression upon 3T3-L1 adipocyte insulin resistance." (PMID 35250844, 2021). "Benefits on insulin-resistance (measured by the HOMA index) and insulin-sensitivity (measured by HOMA β or the WBISI index) have also been reported and are consistent with the results of the present study." (PMID 33063272, 2021). "As expected, the 14 WHR-associated alleles showed directionally consistent enrichment with increased triglycerides, low-density lipoprotein-cholesterol, fasting insulin and HOMA-derived insulin resistance measures." (PMID 34072523, 2021). "Systemic insulin resistance indicators, including serum fasting blood glucose (FBG), fasting insulin (FINS), Homeostatic Model Assessment for Insulin Resistance (HOMA-IR), and hemoglobin A1 (HbA1), were upregulated by the PM2.5 instillation." (PMID 34745386, 2021). "Combined insulin and IGF-1 resistance restricted to the endothelium leads to a potentially favorable adaptation in contrast to pure insulin resistance, with increased Nox4-derived H2O2 generation mediating enhanced whole-body insulin sensitivity." (PMID 34420367, 2021). "A significant strength of this study is the mechanistic findings from chronic administration of flutamide for treating infertility in pregnant rats under conditions of hyperandrogenism and insulin resistance (resulting from co-exposure to DHT and INS)." (PMID 34180022, 2021). "Reduced insulin levels and HOMA-IR (homeostatic model assessment insulin resistance) values are observed in patients suffering from anorexia nervosa." (PMID 34579156, 2021). "Blood glucose and insulin levels, including HOMIA-IR and QUICKI values, blood glucose changes in OGTT and IITT experiments, are usually the common parameters to indicate insulin resistance." (PMID 35049893, 2021).
Insulin resistance (continued). "Limitations in the present study include the following: First, allopurinol treatment did not improve hyperglycemia despite significant amelioration of hepatic steatosis and insulin resistance index such as HOMA-IR and AUC of insulin." (PMID 33972568, 2021). "Insulin has been shown to activate the MAP kinase pathway, despite the presence of insulin resistance in the Akt pathway, leading to oxidative stress in the wall of blood vessels of human subjects with coronary atherosclerosis." (PMID 33400689, 2021). "Indices related to insulin resistance, such as fasting insulin/glucose ratio (FIGR), homeostatic model assessment—insulin resistance (HOMA-IR), and quantitative insulin sensitivity check index (QUICKI), were measured in fasted animals." (PMID 33671110, 2021). "However, hepatic triglyceride levels did weakly correlate with serum glucose (R = 0.32, p < 0.05) suggesting that hepatic lipid levels may impact glycemia (or vice versa) independently of serum insulin which is commonly considered an index of insulin resistance." (PMID 34684643, 2021). "On the other hand, COVID-19 can deteriorate insulin resistance in people with T2DM and T1DM via inducing a proinflammatory milieu that can further lead to lowering insulin sensitivity." (PMID 34680053, 2021). "In the existing literature, it has been confirmed that normal concentration of insulin can improve the uptake of glucose by promoting the translocation of GLUT4, but in the insulin resistance animal models, the promoting effect of insulin on GLUT4 disappeared." (PMID 33967958, 2021). "Correlations between microbial taxa abundance and cytokine production (e.g., IL-1β, TNFA) in insulin-sensitive subjects, and the lack of these associations in insulin-resistant participants, suggest that insulin resistance may affect interactions between gut microbiome and host cytokines’ release." (PMID 35010920, 2021). "Kozyra and colleagues further illustrated that transcriptional change related to steatosis and insulin resistance can be induced in PHH spheroids with pathophysiological FFA, monosaccharides, and insulin." (PMID 34631680, 2021). "Insulin resistance is the main pathological basis of T2DM, which refers to the decrease of insulin utilization rate and decrease of the body's sensitivity to insulin." (PMID 34335798, 2021). "When we examined the potential of AMY to ameliorate HFD-induced glucose intolerance and insulin insensitivity, the respective GTT and ITT results showed improvement of HFD-induced insulin resistance, evidenced by a decrease in the HOMA-IR index." (PMID 34406209, 2021). "The homeostasis model of assessment of insulin resistance (HOMA-IR), fasting insulin levels, fasting glucose levels, among others, were used to assess insulin resistance or sensitivity." (PMID 34682457, 2021). "Insulin resistance and hyperinsulinemia contribute to hyperandrogenemia through reducing hepatic production of SHBG, as well as by direct stimulant effects of excess insulin on the ovarian production of androgens by the ovarian theca." (PMID 34063169, 2021). "One day later, neonatal rats were exposed to either acute normoxic or hypoxic separation (fasting) for 90 min, and blood was sampled for the measurement of insulin and glucose and the calculation of HOMA‐IR as an index of insulin resistance." (PMID 33393733, 2021). "Furthermore, insulin resistance triggered by hormonal changes during pregnancy and relative increments in insulin may promote lipid synthesis and triacylglycerol surplus to deposit as visceral adipose tissue, whereas repeated pregnancies may amplify such effect." (PMID 33413314, 2021). "Insulin resistance in obese and T2DM patients is manifested by decreased insulin-stimulated glucose transport and metabolism in adipocytes and skeletal muscle and impaired inhibition of hepatic glucose output." (PMID 35052549, 2021).
Insulin resistance (continued). "PPAR-α and RAR-β2 agonists improve dyslipidemia in insulin target tissues, and PPAR-γ agonists, such as thiazolidinediones, improve insulin resistance." (PMID 34436451, 2021). "Metformin, as a sensitizer of insulin, has been used for PCOS patients with insulin resistance to facilitate fertility restoration." (PMID 34127011, 2021). "After that, the levels of glucose and insulin in serum, HOMA-IR as an indicator of insulin resistance, the ocular level of oxidative markers, TNF-α, IL-1β, MIPs, and MCP-1 along with ocular gene expression of NF-κB, Nrf2, and miR-146a-5p were evaluated." (PMID 34804425, 2021). "To further confirm the development of insulin resistance in HFD rats, we did IPGTT and IPITT tests, and analysed the major proteins involved in insulin signalling pathway." (PMID 33591626, 2021). "An obese rat model study showed that LWDHW decreased serum triglycerides, nonesterified fatty acid levels, body fat, serum leptin, and insulin levels, suggesting a positive effect of LWDHW in improving insulin resistance." (PMID 34457016, 2021). "Fasting insulin levels increased significantly in the HFGFD-fed group, as well as insulin resistance [homeostatic model assessment of insulin resistance (HOMA-IR)]." (PMID 34014280, 2021). "The study also showed that BPA-treated rats on a standard diet had an increase in serum insulin levels, an elevated homeostatic model assessment of insulin resistance (HOMA-IR) and a reduced insulin sensitivity index (ISI) compared with the control group." (PMID 33467592, 2021). "Insulin, HOMA-IR, and TG indices were increased in HFCD-induced insulin resistance animals compared with controls." (PMID 34037093, 2021). "Other studies proved that insulin resistance was highly involved in CFRD, and impaired insulin responses were also reported in CF patients." (PMID 33659254, 2021). "In parallel, plasma insulin level and HOMA-IR index were improved in the HF-Tiso group, suggesting a protective effect of T. lutea against insulin resistance." (PMID 33525643, 2021). "Gut microbiota, glycaemic control, inflammatory parameters, body mass index, homeostatic model assessment of insulin resistance (HOMA-IR), glucagon-like peptide-1 (GLP-1), and fasting insulin." (PMID 34684378, 2021). "As insulin resistance has been reported to be related to inflammation, high-level insulin release promotes the production of angiogenic factors and pro-inflammatory cytokines, and glucose uptake was decreased in the inflammatory environment, which may aggravate insulin resistance." (PMID 33743811, 2021). "Clinical trials have demonstrated that vitamin K supplementation improved insulin sensitivity index (ISI), disposition index, reduced insulin resistance, 2-h post oral glucose tolerance test (OGTT) glucose, and 2-h post OGTT insulin." (PMID 33766030, 2021). "Insulin resistance was evaluated by homeostatic model assessment of insulin resistance (HOMA-IR) and quantitative insulin-sensitivity check index (QUICKI)." (PMID 34248844, 2021). "As a major signaling adapter of the insulin/IGF-1 signaling pathway, IRS-1 stimulates a variety of downstream pathways to participate in the regulation of insulin resistance and cell differentiation." (PMID 34295306, 2021). "In insulin resistance, a defect in this process reduces GLUT4 expression and displacement in major insulin target organs such as the liver and muscles." (PMID 34094026, 2021). "Insulin serum values and HOMA-IR were significantly higher in Groups 2 and 3 versus Group 1, as was the rate of insulin resistance (p < 0.05)." (PMID 33804476, 2021). "The homeostasis model assessment of insulin resistance (HOMA-IR) is a proxy estimate of IR based upon the relationship between fasting glucose and insulin levels, with higher values of HOMA-IR representing more severe IR." (PMID 34828775, 2021).